IL13 (interleukin 13)
Diseases named in the same sentence as IL13 in open-access papers (continued):
Sharing a sentence is not in itself a finding about the gene and the disease.
pancreatic cancer (continued). "Similar to the synergistic anti-tumor activity of IL-4 cytotoxin and gemcitabine, the combination of IL-13 cytotoxin with gemcitabine exhibited a remarkable and specific anti-tumor impact in pancreatic cancer cells and advanced pancreatic cancer animal models." (PMID 33804263, 2021). "Anti-tumor abilities of IL-13 cytotoxins have been shown in vivo, particularly in IL-13Rα2-positive pancreatic cancer cell lines, and also in animal models of human pancreatic cancer." (PMID 33804263, 2021). "In pancreatic cancer, IL-13 can signal after binding to IL-13Rα2 via the AP-1 pathway, and IL-13Rα2 expression is dependent upon histone acetylation." (PMID 32443847, 2020). "We have previously reported that IL-13Rα2 is a functional receptor as IL-13 mediates signaling in human pancreatic cancer cell lines." (PMID 30572904, 2018). "For example, pancreatic tumor cells expressed cytokine IL-13 to repolarize the nearby macrophages to a tumor-promoting/M2 subtype." (PMID 29379802, 2017). "Focusing on pancreatic cancer, exogenous IL-4 and IL-13 increased the growth of cultured cancer cells, possibly by stimulating growth-promoting pathways such as MAP-kinases." (PMID 28350325, 2017). "IL-13 has been shown to act as an autocrine growth factor in pancreatic cancer that promotes lymph node metastasis and is a major regulator of M2 macrophages to suppress immune surveillance in metastasis." (PMID 27533463, 2016). "Meanwhile increasing evidence has shown that IL-13 contributes to transforming growth factor-beta activation by AP-1 pathway, which induces immunosuppression in patients with pancreatic cancer." (PMID 27351230, 2016). "Next, we evaluated anti-cancer effect of combination of SAHA and IL-13-PE in IL-13Rα2-positive pancreatic cancer model (HS766T and MIA-PaCa2)." (PMID 21477288, 2011). "HDAC inhibition provides a novel opportunity in designing combinatorial therapeutic approaches not only in combination with IL-13-PE but with other immunotoxins for therapy of pancreatic cancer and other cancers." (PMID 21477288, 2011). "More importantly, HDAC inhibitors sensitized pancreatic tumor cells to IL-13-PE and mediated enhanced sensitivity even though these cells did not naturally express IL-13Rα2." (PMID 21477288, 2011). "As we have shown that IL-13 can upregulate Matrix metalloproteinases (MMPs) expression in IL-13Rα2 expressing pancreatic cancer cell lines, we investigated the impact of IL-13Rα2 upregulation by HDAC inhibitors by examining IL-13 induced MMPs expression." (PMID 21477288, 2011). "Furthermore, HDAC inhibitors dramatically sensitised pancreatic cancer cells to IL‐13‐PE cytotoxicity in vitro and in animal models of human pancreatic cancer." (PMID 38685487, 2024). "In addition, the activation of MAPK, PI3K-Akt, YAP-TAZ, and JAK-STAT3 signaling pathways by Kras in pancreatic cancer cells results in the upregulation of various suppressive cytokines and chemokines, such as IL-4, IL-6, IL-13, CSF1, and MCP-140,41." (PMID 37184030, 2023). "Furthermore, overexpression of IL-13 in pancreatic cancer tissues and the high co-expression of IL-13 and IL-4Rα correlated with a higher risk of lymph node metastasis." (PMID 35409019, 2022). "Besides the direct mitogenic effects of IL-13 on pancreatic cancer cells, tumor-cell-derived IL-13 along with IL-13 produced by other cells in the TME-like mast cells stimulated the proliferation of pancreatic stellate cells (PSCs)." (PMID 33804263, 2021). "The aim of this review was to summarize knowledge about IL-4 and IL-13 and their receptors in pancreatic cancer in order understand the implication of IL-4 and IL-13 and their receptors for pancreatic tumorigenesis and progression and for developing possible new diagnostic and therapeutic targets." (PMID 33804263, 2021).
pancreatic cancer (continued). "IL13Rα2 was hypothesized to be a decoy receptor for IL13Rα1 and the type II IL-4R complex, but updated evidence suggests that IL-13 may signal through IL-13Rα2 to promote pancreatic cancer cell proliferation and invasion." (PMID 33804263, 2021). "Furthermore, gene transfer of IL-13Rα2 into tumors dramatically sensitized tumors to IL-13 cytotoxin therapy, which was also observed in pancreatic cancer." (PMID 33804263, 2021). "In addition, high IL-13 immunoreactivity was determined in the ductal cancer cells in 43% (30 of 70) of pancreatic cancer tissues." (PMID 33804263, 2021). "In pancreatic cancer, activated mast cells promote tumor progression by IL-13 and tryptase." (PMID 30808413, 2019). "Gabitass and his colleague have also reported that IL-13 from myeloid-derived suppressor cells in pancreatic cancer could promote the tumor growth and metastases." (PMID 27351230, 2016). "Though we did not investigate the presence of metastasis in this model, the pancreatic tumor cells collected from lymph nodes metastasis were much more sensitive to IL-13-PE in vitro than compared with primary tumor cells indicating higher level of IL-13Rα2 in metastatic lesion." (PMID 23421960, 2013). "As expected, IL-13 induced STAT6 phosphorylation in IL-13Rα2-negative pancreatic cancer cell lines." (PMID 21477288, 2011). "Pancreatic tumors were also successfully targeted by IL-13-PE in an animal model of human cancer." (PMID 21477288, 2011). "In vitro cytotoxicity assays and in vivo testing in animal tumor models were performed to determine whether HDAC inhibitors could enhance anti-tumor effects of IL-13-PE in pancreatic cancer." (PMID 21477288, 2011). "As HDAC inhibition increased IL-13Rα2 expression in IL-13Rα2-negative but not in normal cell lines, we examined whether HDAC inhibition enhanced the anti-cancer effect of IL-13-PE in IL-13Rα2-negative pancreatic cancer cell lines." (PMID 21477288, 2011). "In addition, it was reported that bispecific ligand-directed toxins DTEGF13 (catalytic fragment of diphtheria toxin linked to human EGF and IL-13) had high efficacy and decreased toxicity in PANC-1 and MIAPaCa-2 cells and in a mouse model of human pancreatic cancer." (PMID 33804263, 2021). "Interestingly, 15 of 16 (94%) specimens resected from PDAC patients exhibiting high-level co-expression of IL-13 and IL-4R had lymph node metastases, which reveals that IL-13 in conjunction with IL-4R in the pancreatic cancer cells seems to facilitate lymph node metastasis." (PMID 33804263, 2021). "Thus, there is the possibility that IL-13, in addition to imposing direct stimulating effects on pancreatic cancer cell progression, may also contribute to the inhibition of anti-tumor immune mechanisms, thereby facilitating tumor spread." (PMID 33804263, 2021). "Thus, a novel combination of HDAC inhibitors and IL-13-PE may have a prominent role in pancreatic cancer or other cancer therapies in the clinic." (PMID 21477288, 2011). "Consequently, the use of HDAC inhibitors may open a new avenue of treating pancreatic cancer when combined with IL-13-PE." (PMID 21477288, 2011). "As cytokines such as IL-4 and IL-13 play a vital role in the interaction of tumour cells and components of the TME, their understanding is crucial in order to design better therapies for pancreatic cancer." (PMID 35409019, 2022). "We took advantage of upregulation of IL-13Rα2 in pancreatic cancer cell lines and hypothesized that HDAC inhibitors may enhance the sensitivity of IL-13 receptor-targeted immunotoxin, IL-13-PE, in pancreatic cancers." (PMID 21477288, 2011). "IL-13Rα2-negative pancreatic cancer cell lines (Panc-1 and ASPC-1) were implanted in the flanks of immunodeficient mice and treated with two different HDAC inhibitors, TSA and SAHA followed by IL-13-PE immunotoxin." (PMID 21477288, 2011).
pancreatic cancer (continued). "Finally, using multiplex analysis, we find that IL-5, but not IL-4 or IL-13 is hypersecreted from colon and pancreas tumors obtained from mice treated with Th2 cells." (PMID 36376448, 2023). "In pancreatic cancer, IL-13 or IL-4 is not studied in clinical trials currently." (PMID 35409019, 2022). "We have also demonstrated that IL-13 can enhance pancreatic cancer invasion and metastasis after binding to IL-13Rα2 via the upregulation of extracellular-signal-regulated kinase (ERK) and Matrix metallo-proteinases (MMPs) in the murine orthotopic pancreatic cancer model." (PMID 32443847, 2020). "Similarly, as expected, IL-13 did not induce MMPs expression in IL-13Rα2-negative pancreatic cancer cell lines." (PMID 21477288, 2011). "It is important to note that while HDAC inhibition enhanced the remarkable anti-cancer effects of IL-13-PE in pancreatic cancer models in vivo by upregulating IL-13Rα2 in the tumors, no significant upregulation of IL-13Rα2 expression was observed in any vital organs." (PMID 21477288, 2011). "Exogenous IL-13 was shown to induce the expression of MMPs including MMP-9, MMP-12, and MMP-14, which were related to pancreatic cancer invasion in IL-13Rα2-positive pancreatic cancer cells independent of STAT6 phosphorylation." (PMID 33804263, 2021).
periodontitis (31 papers, 2014 to 2025). An acute or chronic inflammatory process that affects the tissues that surround and support the teeth. "IL-13 −1112C/T C allele had a weak relationship with the periodontitis risk with OR (95% CI), 0.91 (0.62–1.21)." (PMID 35046930, 2021). "The present study on the association between the IL-13 -1112C/T gene polymorphism and periodontitis is different." (PMID 29415708, 2018). "The aim of the current study was to investigate the link between this IL-13 -1112 polymorphism and susceptibility to periodontitis." (PMID 29415708, 2018). "Several studies have examined the association between the IL-13 -1112C/T polymorphism and the risk of periodontitis." (PMID 29415708, 2018). "The association between the IL-13 -1112 gene polymorphism and the susceptibility to periodontitis has been studied recently." (PMID 29415708, 2018). "The IL-13 -1112 gene polymorphism is associated with susceptibility to periodontitis, which has been studied in recent years." (PMID 29415708, 2018). "Studies have found that periodontitis in the gingival tissue is associated with a significant increase in IgE and that IL-13 can stimulate cells in periodontal lesions to produce and fight against periodontal pathogens that express lipopolysaccharide." (PMID 29415708, 2018). "Recently, the study of IL-13 gene polymorphisms and their relationships with periodontitis contributed to our understanding, but the results of the current study were not clear and some issues did exist." (PMID 29415708, 2018). "Similarly, IL-13 −1112C/T T allele also had a weak relationship with the periodontitis development with OR (95% CI), 0.92 (0.45–1.39)." (PMID 35046930, 2021). "Despite these limitations, this meta-analysis showed that the IL-13 -1112 gene polymorphism might be associated with susceptibility to periodontitis." (PMID 29415708, 2018). "The pooled analyses using these models indicated that the IL-13 -1112C/T polymorphism was significantly associated with susceptibility to periodontitis (CC vs TT: OR = 0.615, 95% CI = 0.395–0.957; CTvsTT: OR = 0.518, 95% CI = 0.323–0.830;and TT vs CT + CC: OR = 1.739, 95% CI = 1.130–2.676)." (PMID 29415708, 2018). "IL-13 gene polymorphisms may play roles in periodontitis by affecting other genes that are undetected." (PMID 29415708, 2018). "Therefore, the IL-13 -1112 gene polymorphism and its possible correlation with periodontitis must be analyzed from an evidence-based medicine perspective." (PMID 29415708, 2018). "Therefore, understanding the biological role of IL-13 and its gene polymorphisms is necessary for an in-depth study of periodontitis." (PMID 29415708, 2018). "According to the results of this study, the association of the IL-13 -1112 gene polymorphism with periodontitis may be due to differences in the disease (CP and AgP), which are presumably due to factors such as race, region, predilection, suspicious disease-causing bacteria and etiology." (PMID 29415708, 2018). "Therefore, in addition to the need for an in-depth study of a single gene, there is also a need for a comprehensive study of a number of genetic loci to expand the sample size and better reveal the roles of IL-13 gene polymorphisms in periodontitis development." (PMID 29415708, 2018). "The IL-13 -1112 polymorphism may be associated with susceptibility to periodontitis." (PMID 29415708, 2018). "Therefore, this meta-analysis of the IL-13-1112C/T gene polymorphism and periodontitis susceptibility used case-control studies to conduct a systematic quantitative analysis of the IL-13-1112C/T gene polymorphism and susceptibility to periodontitis and to provide evidence-based medical evidence." (PMID 29415708, 2018). "Overexpression of microRNA-146a improve periodontitis by downregulating IL-13 and inhibiting the proliferation of PDLSCs derived from both periodontitis-affected teeth and healthy teeth." (PMID 39959357, 2025).
periodontitis (continued). "MicroRNA-146a was downregulated and IL-13 was upregulated in PDLSCs derived from periodontitis-affected teeth." (PMID 39959357, 2025). "Specifically, Allium sativum (garlic) extract has been shown to upregulate anti-inflammatory cytokines, such as IL-10 and IL-13, which significantly reduce alveolar bone resorption in experimental periodontitis models." (PMID 41477399, 2025). "The highest IL-13 mean value was found in the experimental group, comprising rats induced with periodontitis and treated with Chinese betel leaf extract, measuring 155.209 ± 7.555 pg/mL." (PMID 39539670, 2024). "A multiple regression analysis was performed to evaluate the impact of AD diagnosis and the covariates age, gender, smoking status, and periodontitis severity on the GCF levels of IL-13, IL-31, and TSLP." (PMID 37958576, 2023). "IL-13 inhibits the destructive activity of fibroblasts in periodontitis and activates the Transforming growth factor beta (TGF-β), which has the function of stimulating cell growth, playing an important role in connective tissue remodeling." (PMID 37026605, 2023). "While the levels of IL-10 and IL-13, which are anti-inflammatory cytokines that regulate immune responses, decreased in the animal model of periodontitis, the levels of the same biomarkers increased in the group orally administered TEES-10®." (PMID 36005241, 2022). "Considering the importance of IL-13 in the development of periodontitis, a case-control study with a large sample size must be developed to explore the correlation between the IL-13 -1112C/T polymorphism and periodontitis." (PMID 29415708, 2018). "The Chinese and English terms used to search the literature included “periodontitis”, “periodontal disease”, “IL 13”, “IL-13”, and “interleukin-13”." (PMID 29415708, 2018). "In light of the more marked expansion of the pool of ILC2s in periodontitis, we also explored mRNA expression of ILC2s-related cytokines, namely IL-5 and IL-13; we also determined expression of IL-33 since it is a pivotal regulator of function of ILC2s." (PMID 28861078, 2017). "Induction of periodontitis in wild mice markedly increased expression of IL-33 but expression levels of IL-5 and IL-13 resembling those of sham-operated groups." (PMID 28861078, 2017). "In addition to IL-1β, levels of IL-2, IL-8, and IL-13 were significantly elevated in the GCF of periodontitis sites compared to healthy and gingivitis sites (p < 0.05)." (PMID 41303313, 2025). "Chronic periodontitis is characterized by heavy infiltration with B-lymphocytes and these are important effector cells mediating inflammation and destruction in periodontitis and thus could explain the strong IL-13 loading." (PMID 36791096, 2023). "We also observed that six molecules (IL-4, IL-5, IL-12, IL-13, IL-21, and IL-23) were intimately related in the periodontitis sites of all evaluated groups, regardless of risk factors." (PMID 37835794, 2023). "The polymorphisms for IL-4 and IL-13 of Th2 cytokine family are not found to be associated with the pathogenesis of periodontitis." (PMID 35046930, 2021). "The polymorphisms for the members IL-4 and IL-13 of Th2 cytokine family are not found to be associated with the pathogenesis of periodontitis." (PMID 35046930, 2021). "Elevated levels of IL-13 have been detected in T-cells of severe periodontitis patients." (PMID 34680779, 2021). "Interestingly, however, induction of periodontitis in AMPK KO mice further increased IL-33 mRNA expression and also caused significant increases in expression levels of both IL-5 and IL-13." (PMID 28861078, 2017). "Similarly, in periodontitis IL-13 can have anti-inflammatory and proinflammatory effects." (PMID 36791096, 2023). "The present findings showed that the members IL-4 and IL-13 of Th2 cytokine family may not be associated with the pathogenesis of periodontitis." (PMID 35046930, 2021).
periodontitis (continued). "Taken together, these results suggest that the members IL-4 and IL-13 of Th2 cytokine family may not be associated with the pathogenesis of periodontitis." (PMID 35046930, 2021). "Importantly, however, upregulation of IL-5 and IL-13 in AMPK KO/periodontitis mice further substantiates our working hypothesis that AMPK is a modulator/regulator of ILCs." (PMID 28861078, 2017). "In contrast, patients with aggressive periodontitis were found to have lower levels of other cytokines, including CCL2, M-CSF, GM-CSF, IL-1ra, IL-10, and IL-13." (PMID 38139161, 2023). "In subjects with periodontitis, lower levels of IFN-γ, IL-6, IL-10, IL-13 and I-TAC were found in the Sp group compared with those in the Cp group." (PMID 33417619, 2021). "During the process of periodontitis, type II helper T lymphocytes (TH2) secrete IL-4, IL-13 and other cytokines that are conducive to B cell humoral immunity and improve the symptoms of inflammation." (PMID 29415708, 2018). "Therefore, this study aims to compare the GCF levels of IL-13, IL-31, and TSLP between AD patients and healthy controls and to explore the impact of periodontitis and AD on the GCF levels of these molecules." (PMID 37958576, 2023). "Nonetheless, it is intriguing that IL-33, but not IL-5 or IL-13, is increased in the WT/periodontitis group but knockdown of AMPK “unleashes” expression of ILCs-2-related cytokines." (PMID 28861078, 2017). "On day 7 after periodontitis induction and treatment administration, blood was drawn from the inferior vena cava, totaling 10 mL, to obtain blood serum for determining the levels of proinflammatory cytokines TNF-α, IL-1β, and anti-inflammatory cytokines IL-10, IL-13 through ELISA examination." (PMID 39539670, 2024). "Similarly, for IL-13 levels, the Pepper Elder extract group does not differ significantly from the Pristine group and the positive control group (p > 0.05) but differs significantly from the negative control group, which consisted of rats induced with periodontitis without treatment (p < 0.05)." (PMID 39539670, 2024).